RNMT (RNA guanine-7 methyltransferase)
Description:
Catalytic subunit of the mRNA-capping methyltransferase RNMT:RAMAC complex that methylates the N7 position of the added guanosine to the 5'-cap structure of mRNAs. Binds RNA containing 5'-terminal GpppC.
Synonyms: hCMT1; hMet; RG7MT1; N7-MTase; CMT1; CMT1c; cm1p
Tractability: Small molecule: a structure with a bound ligand is known; it has a binding pocket of medium quality. PROTAC: ubiquitination databases record sites on it; its protein half-life has been measured; a small molecule that binds it is known.
Target class: Enzyme; Transferase
Gene: Protein-coding gene on chromosome 18 (13,726,660 to 13,764,556, forward strand). Ensembl gene ENSG00000101654.
Subcellular location: Nucleus
Subcellular location (Human Protein Atlas): Nucleoplasm; Nucleoli fibrillar center
Pathways (Reactome):
Disease: RNA Pol II CTD phosphorylation and interaction with CE during HIV infection
Gene expression (Transcription): RNA Pol II CTD phosphorylation and interaction with CE
Metabolism of RNA: mRNA Capping
Gene Ontology:
Molecular function: mRNA 5'-cap (guanine-N7-)-methyltransferase activity; protein binding; RNA binding
Biological process: 7-methylguanosine mRNA capping; RNA 5'-cap (guanine-N7)-methylation
Cellular component: fibrillar center; methyltransferase complex; mRNA cap methyltransferase RNMT:RAMAC complex; mRNA capping enzyme complex; nucleoplasm; nucleus; receptor complex
Genetic constraint (gnomAD): Loss-of-function variants: 16 observed, 26.41 expected, observed/expected ratio (o/e) 0.61, 90% interval 0.41 to 0.92. The upper end of that interval is the gene's LOEUF score, 0.92, which puts it in group 3 of 6, group 1 being the genes least tolerant of losing a copy. Missense variants: 330 observed, 373.74 expected, observed/expected ratio (o/e) 0.88, 90% interval 0.81 to 0.97. Synonymous variants: 117 observed, 124.47 expected, observed/expected ratio (o/e) 0.94, 90% interval 0.81 to 1.1.
Homologues: Orthologues: chimpanzee RNMT (99% identical), macaque RNMT (96% identical), dog RNMT (90% identical), pig RNMT (88% identical), guinea pig RNMT (85% identical), rabbit RNMT (83% identical), mouse Rnmt (75% identical), rat Rnmt (72% identical), tropical clawed frog rnmt (54% identical), zebrafish rnmt (49% identical), Drosophila melanogaster Rnmt (36% identical), Caenorhabditis elegans tag-72 (28% identical).
Diseases named in the same sentence as RNMT in open-access papers:
RNMT is named in the same sentence as 20 diseases in open-access papers, as found by Europe PMC text mining. Sharing a sentence is not in itself a finding about the gene and the disease. The quoted sentences say what the papers report.
breast carcinoma (5 papers, 2019 to 2025). "In this study we provide evidence to suggest RNMT should be explored as a therapeutic target in breast cancers harbouring PI3K p110α mutations." (PMID 30991934, 2019). "Taken together, these data demonstrate that breast cancer cells with activating mutations in PIK3CA are selectively sensitive to RNMT inhibition." (PMID 30991934, 2019). "Breast cancer cell lines with oncogenic PI3KCA mutations are most sensitive to RNMT inhibition." (PMID 40924934, 2025). "Strengthening the link between PIK3CA mutations and RNMT inhibition, breast cancer cell lines and mammary epithelial cells, which were insensitive to RNMT siRNA transfection, could be rendered sensitive by the expression of PIK3CA oncogenic mutants." (PMID 30991934, 2019). "Inhibition of RNMT expression or function reduces cell proliferation rates and induces apoptosis across many cell lineages, including HeLa cells, breast cancer cell lines and primary T cells." (PMID 40924934, 2025). "Collectively, these findings provide evidence to support RNMT as a therapeutic target in breast cancer and suggest that therapies targeting RNMT would be most valuable in a PIK3CA mutant background." (PMID 30991934, 2019). "In this study, we investigated the impact of RNMT depletion on the proliferation of a panel of breast cancer cell lines." (PMID 30991934, 2019). "When cellular RNMT activity was experimentally reduced by 50%, the proliferation rate of non-transformed mammary epithelial cells was unchanged, whereas a subset of breast cancer cell lines exhibited reduced proliferation and increased apoptosis." (PMID 30991934, 2019). "We investigated the proliferative response of a panel of breast cancer cell lines and a normal mammary epithelial cell line to a reduction in RNMT expression." (PMID 30991934, 2019). "Collectively, these data indicate that breast cells harbouring oncogenic PIK3CA mutations have enhanced dependence on RNMT (mRNA cap methylation) for proliferation and survival, making RNMT a promising therapeutic target in PIK3CA mutant breast cancer." (PMID 30991934, 2019). "Collectively, these results demonstrate that PI3K p110α signalling contributes to RNMT dependency in breast cancer cell lines expressing oncogenic PIK3CA mutants." (PMID 30991934, 2019). "RNMT targeting in a panel of breast cancer cell lines induces apoptosis." (PMID 40924934, 2025). "RNMT is a promising therapeutic target in PIK3CA (phosphatidylinositol-4,5- bisphosphate 3-kinase catalytic subunit alpha gene) mutant breast cancer, as PIK3CA mutations in breast cells depend on RNMT (mRNA cap methylation) for their survival and proliferation." (PMID 38402266, 2024). "For example, RNMT (RNA guanine-7 methyltransferase) demonstrated an association with CDK1-cyclin B1 to sync mRNA G1 phase transcription and impact mRNA surveillance and it has also been found to potentially correlate with immune cell infiltration in breast cancer (BC)." (PMID 38735973, 2024). "By contrast, the proliferation of IMECs and other breast cancer cell lines expressing WT PIK3CA (BT-549, MDA-MB-231, CAMA-1 and ZR-75-1) was unaffected by RNMT siRNA transfection." (PMID 30991934, 2019). "Of note, breast cancer cell lines with PTEN loss (CAMA-1, BT-549 and ZR-75-1) were not sensitive to RNMT inhibition, suggesting that PIK3CA mutations, rather than PTEN loss, promotes RNMT dependency in breast cancer." (PMID 30991934, 2019). "The maturation of the RNA cap involving guanosine N-7 methylation, catalyzsed by the HsRNMT (RNA guanine-7 methyltransferase (HsRNMT)-RAM (RNA guanine-N7 methyltransferase activating subunit (RAM) complex, is currently under investigation as a novel strategy to combat PIK3CA -mutant breast cancer." (PMID 39869500, 2025). "However, in breast cancer cell lines and T cells, Myc expression does not alter upon RNMT knockdown." (PMID 40924934, 2025).
breast carcinoma (continued). "Alternatively, RNMT inhibition may affect protein expression similarly in all breast cancer cell lines, regardless of PIK3CA status; cells expressing PIK3CA may have increased dependency on a subset of RNMT-dependent proteins as a mechanism of oncogene addiction." (PMID 30991934, 2019). "To address whether different breast cancer cell lines exhibit differential sensitivity to inhibition of RNMT, we reduced RNMT expression in a panel of breast cancer cell lines and non-transformed cells by transfection of RNMT siRNA (specific inhibitors of RNMT are not currently available)." (PMID 30991934, 2019).
glioma (5 papers, 2020 to 2025). A benign or malignant brain and spinal cord tumor that arises from glial cells (astrocytes, oligodendrocytes, ependymal cells). "The downregulation of B7-H6 expression in glioma stem-like cells resulted in decreased RNA guanine-7 methyltransferase (RNMT) and decreased Myc levels." (PMID 39408655, 2024). "In the context of B7–H6, knockdown of this checkpoint using siRNAs in glioma CSCs resulted in their hampered proliferation profile through downregulation of c-Myc and repressing RNA guanine-7 methyltransferase (RNMT) activity." (PMID 38144305, 2023). "In malignant brain tumors (Glioma), B7-H6 (B7 homologue 6) is expressed abnormally and RNMT expression was significantly decreased in B7-H6 knock-down glioma stem-like cells (GSLCs) suggesting RNMT role in B7-H6 tumor cell proliferation enhancement via the c-Myc/RNMT Axis." (PMID 38402266, 2024).
acute myeloid leukemia (1 paper, 2025). Acute myeloid leukemia (AML) is a group of neoplasms arising from precursor cells committed to the myeloid cell-line differentiation. "Eukaryotic translation initiation factor 4E (eIF4E), a prooncogenic protein increased in acute myeloid leukemia (AML), specifically binds to m7 G caps and stimulates the export and translation of RNMT and RNGTT." (PMID 40483535, 2025).
cervical adenocarcinoma (1 paper, 2011). An adenocarcinoma arising from the cervical epithelium. "The interaction between endogenous cellular RNMT and RAM was confirmed by immunoprecipitations performed on extracts of HeLa cells (human cervical adenocarcinoma-derived), human primary T lymphocytes, and SAOS-2 cells (human osteosarcoma-derived)." (PMID 22099306, 2011).
cervical cancer (1 paper, 2019). A primary or metastatic malignant neoplasm involving the cervix. "Inhibition of RNMT and RAM has been observed to induce apoptosis in HeLa cells, a cervical cancer cell line." (PMID 30991934, 2019).
tumor (7 papers, 2019 to 2024). "Likewise, RNA guanine-7 methyltransferase (RNMT) could also catalyze the methylation at the guanine N7 position, which is associated with tumor growth." (PMID 35860263, 2022). "RNMT was downregulated in GBM and UCEC tumours, consistent with the overall downregulation of RNMT in brain and gynaecological cancers, whereas the expression of FAM103A1 increased in these cancers." (PMID 39041608, 2024). "Such information, along with deeper understanding of the mechanism of action of the RNMT–RAM complex, is critical for drug discovery efforts aiming to inhibit the cap methyltransferase activity—and thus gene expression and translation—in tumour cells or in parasites." (PMID 31329932, 2019).
cancer (6 papers, 2019 to 2025). A tumor composed of atypical neoplastic, often pleomorphic cells that invade other tissues. "Pan-cancer analysis shows that RNMT expression is associated with prognosis in certain cancer types." (PMID 40924934, 2025). "There was a uniquely higher mutation frequency of RNMT in different cancer types, particularly in UCEC, STAD, SKCM and LUAD." (PMID 39041608, 2024). "In these cells and other cancer cell lines in which they have been investigated, RNMT and RAM are found in complex with each other with minimal detection of their monomeric forms." (PMID 40924934, 2025). "Given the critical role of RNMT in gene expression, cell proliferation and cell transformation, RNMT is a promising candidate for cancer therapeutics." (PMID 40924934, 2025). "Taken together, RNMT plays a critical role in tumorigenesis and it is a valid target for development of cancer therapeutics." (PMID 38402266, 2024). "This information is critical for the drug discovery efforts that consider RNMT as a promising anti-cancer target." (PMID 31329932, 2019). "This gives an important indication of which cancer types and patient populations are most likely to response to RNMT inhibitors." (PMID 30991934, 2019). "As a result, RNMT is investigated as a potential therapeutic target in cancer or immune disorders." (PMID 40924934, 2025). "The assay will enable identifying and characterizing potent inhibitors towards development of chemical tools to investigate the roles RNMT may play in various cancers, and development of selective antiviral therapeutics." (PMID 38402266, 2024). "However, oncogenic mutations in the gene PIK3CA, which encodes the p110α catalytic subunit of PI3K, were found in five out of six cancer cell lines exhibiting enhanced sensitivity to RNMT inhibition." (PMID 30991934, 2019). "For the m7G cap writers, we observed an opposing expression pattern of RNMT and FAM103A1 in cancer." (PMID 39041608, 2024). "Expression of oncogenic PIK3CA mutants does not alter RNMT expression and activity; therefore, it is possible that the contribution of RNMT to other cancer types may have been overlooked in the absence of RNMT expression deregulation." (PMID 40924934, 2025).
heart disease (1 paper, 2021). "Further potentially disease-relevant protein candidates without a known functional relation to hypertrophy, fibrosis or decompensated heart disease were SLTM, HNRNPLL, FIP1L1, RNMT, KRT18 and PUF60 and the downregulated NUDT4, GCAT, KIDINS220 and ARVCF." (PMID 34937869, 2021).
RNMT also shares sentences with these, for which no sentence is quoted: Williams-Beuren Syndrome (2 papers); demyelinating peripheral neuropathy (1); immune disorders (1); inflammatory demyelinating neuropathy (1); influenza (1); lung carcinoma (1); lymphoma (1); malignant brain tumors (1); neurological disorder (1); osteosarcoma (1); polyneuropathies (1); primary progressive multiple sclerosis (1).